ESR1 (estrogen receptor 1)
Diseases named in the same sentence as ESR1 in open-access papers (continued):
Sharing a sentence is not in itself a finding about the gene and the disease.
breast cancer (continued). "Based on these findings, we conclude that our preclinical model faithfully recapitulates the phenotypic characteristics of tumors from breast cancer patients harboring ESR1 mutations and represents an excellent model system for therapeutic studies." (PMID 35881485, 2022). "We next sought to establish if the genes upregulated in our ESR1 mutant MCF7 cells are also more highly expressed in breast cancers with ESR1 mutations." (PMID 36198774, 2022). "ERα, encoded by the ESR1 gene, is highly overexpressed in hormone-responsive cancers, such as ovarian, endometrial, and breast cancers." (PMID 36358773, 2022). "This targets the estrogen receptor in breast cancer and also degrades clinically important ESR1 variants (Y537S and D538G)." (PMID 36120561, 2022). "Acquired mutations in the ligand-binding domain (LBD) of the gene encoding estrogen receptor α (ESR1) are common mechanisms of endocrine therapy resistance in patients with metastatic ER+ breast cancer." (PMID 35881485, 2022). "ESR1 mutations have been recently associated with resistance to endocrine therapy in metastatic breast cancer and their detection has led to the development and current evaluation of novel, highly promising therapeutic strategies." (PMID 35954453, 2022). "Previous studies discovered that ESR1 mutation was associated with bone metastasis of breast cancer." (PMID 35402245, 2022). "ESR1 mutations were detected in 9 (7.4%, 95% Wald asymptotic confidence interval (CI) 2.8–12.1%) out of 121 primary breast cancer specimens." (PMID 35501333, 2022). "The ESR1 Y537S mutation, in particular, is associated with development of resistance to most endocrine therapies used to treat breast cancer." (PMID 35881485, 2022). "ESR1 has the function of encoding estrogen receptor and has been the focus of breast cancer research for a long time, but it is also related to gastric cancer and other types of cancer." (PMID 35686089, 2022). "Testing for ESR1 mutation in ongoing clinical trials and in hormonal therapy for breast cancer is highly recommended." (PMID 36229710, 2022). "In breast cancer xenograft models with activating mutations in the ESR1, as well as tamoxifen-sensitive and tamoxifen-resistant breast cancer xenografts, GDC-0810 demonstrates potent anti-tumor activity." (PMID 36229710, 2022). "ESR1 mutations are also enriched in patients with localized breast cancer receiving neoadjuvant endocrine therapy." (PMID 35881485, 2022). "A recent study has shown that nearly one-third of locoregional recurrent tumors in patients who have completed definitive treatment for ER+ breast cancer also harbor ESR1 mutations." (PMID 35881485, 2022). "Together these results show that chemical reduction of ERα cellular lifetime is not necessarily the most crucial parameter for transcriptional antagonism in ESR1 mutated breast cancer cells." (PMID 35575456, 2022). "We employed a collection of genes associated to endocrine therapy resistance in breast cancers expressing estrogen receptor (ESR1) and ERBB2 (HER2) and identified a significant enrichment (NES 1.56)." (PMID 36359853, 2022). "In particular, our data shows that GWAS variants associated with breast cancer risk not only are enriched in regions that are bound by the estrogen receptor but also tend to alter the way in which ESR1 binds these regions." (PMID 35061909, 2022). "Along the same line, ESR1 mutations were enriched in liver metastases of the hormone receptor (HR)+/HER2pos breast cancers." (PMID 35983233, 2022). "Our results confirm these findings and show that other ESR1 mutations similarly upregulate ISG expression in breast cancer cells." (PMID 36198774, 2022). "Estrogen receptor mutation (ESR1 mutation) is one of the common mechanisms by which breast cancer becomes resistant to additional therapies from SERMs or AIs." (PMID 36229710, 2022).
breast cancer (continued). "This is the first report to provide clinical evidence that an ESR1 mutation interrogated by ddPCR is linked with primary resistance to adjuvant ET in ER+ breast cancer." (PMID 35501333, 2022). "The reduced interaction between the super enhancer and ESR1 promoter locus in LATS1/2 deficient cells was further validated by multiplexed in-situ UMI-4C-seq in another ER+ breast cancer line T47D." (PMID 35217640, 2022). "GATA3 is mutated in >10% of breast cancers and directly impacts ESR1 enhancer accessibility, thereby altering binding potential and transcriptional targets in tumor cells." (PMID 36517508, 2022). "As for the ESR1-e6>fusion genes, only a handful of functionally active ESR1 fusion proteins have been studied to date and therefore ESR1 fusion events remain an understudied form of somatic mutation in breast cancer." (PMID 36686845, 2022). "Although point mutations and ESR1 amplifications have been linked with breast cancer metastasis and therapy resistance, the role of ESR1 splicing in the tumor response to endocrine therapies remains to be determined." (PMID 35044822, 2022). "We detected a low ESR1 mutation allele frequency, ranging from 0.01 to 8.37%, in primary ER+ breast cancer." (PMID 35501333, 2022). "ESR1 gene mutations in breast cancer tumor ER are frequently associated with the development of endocrine resistance." (PMID 35505937, 2022). "Next to mutations in ESR1, other mechanisms have been proposed to induce estrogen-independent growth of breast cancer cells, highlighting the complex gene regulation of ESR1." (PMID 35628441, 2022). "ESR1 mutations are found in nearly one-third of all patients with metastatic ER+ breast cancer and are associated with worse clinical outcomes, including overall survival." (PMID 35881485, 2022). "Clinically, CDK4/6 inhibitors are the preferred systemic therapy for the treatment of patients with metastatic ER+ breast cancer who have become resistant to endocrine therapies; including through acquisition of ESR1 mutations." (PMID 35881485, 2022). "ESR1 mutations have recently been discovered in the plasma of ER-positive metastatic breast cancer patients, and ESR1-mutated ctDNA has been identified as a predictive marker for response to aromatase inhibitor therapy." (PMID 35887191, 2022). "Recently, the key role of the acquisition of ligand-independent ESR1 mutation in breast cancer as a common mechanism of resistance to hormonal therapy was discovered." (PMID 33277683, 2021). "This naturally occurring ESR1 mutation will provide an important research model for the future basic studies of resistance mechanisms in breast cancer endocrine therapy." (PMID 34651424, 2021). "Mutations within the ERα encoding gene, ESR1, are frequently acquired in HR+ breast cancer and were only recently recognised as a clinically relevant entity." (PMID 33671468, 2021). "In brief, the altered expression pattern of FOXM1/GATA3/FOXA1/ESR1-associated lncRNAs in breast cancer suggests future assessment of the functional role of these genes in the development of breast neoplasms." (PMID 34094972, 2021). "For instance, ESR1 encodes estrogen receptor alpha and its role in the development, progress, and drug resistance of breast cancer is well documented." (PMID 33558504, 2021). "Previous studies reported that the ESR1 mutations were commonly observed in recurrent breast cancer with resistance to hormonal therapy." (PMID 34795255, 2021). "Recently, mutations in ESR1 were identified as acquired mechanisms of resistance to ET, found in 12% to 55% of metastatic breast cancers treated previously with ET." (PMID 33937624, 2021). "Previous studies on ESR1 focused on breast cancer, and breast cancer patients highly expressing the ESR1 gene were shown to have a better prognosis; however, recent studies showed that ESR1 is also associated with breast cancer liver metastasis." (PMID 34671598, 2021).
breast cancer (continued). "In contrast to the high rate of ESR1 mutation in advanced breast cancer, the prevalence of resistance mutations in primary breast tumors has been reportedly very low, ranging from 0% to 7% in published studies." (PMID 33937624, 2021). "Estrogen receptor 1 (ER-alpha) is involved in regulating gene expression, and is associated with breast cancer." (PMID 34828279, 2021). "ESR1, also known as estrogen receptor alpha, is medically detected with mutation in many human cancer samples, such as breast cancer." (PMID 34311656, 2021). "Over two-thirds of breast cancers express estrogen receptor α protein (encoded by ESR1) which plays a role in the tumourigenesis of breast cancer." (PMID 34930150, 2021). "ESR1 mainly encodes estrogen receptor á, which is closely related to breast cancer and endometrial cancer, and some studies have shown that the estrogen receptor is also related to gastric cancer." (PMID 34421596, 2021). "The ESR1 gene encodes Estrogen Receptor alpha (ERα), which plays a role in the tumourigenesis of breast cancer." (PMID 34930150, 2021). "In line with previous studies, we also reported ESR1 mutations in primary breast cancer at a low allelic frequency." (PMID 33722295, 2021). "Somatic mutations in the ligand‐binding domain of oestrogen receptor 1 (ESR1) can cause resistance to endocrine therapy in breast cancer." (PMID 34651424, 2021). "To our knowledge, we have conducted the largest study of ESR1 ET resistance mutations in treatment-naïve primary breast cancer." (PMID 33937624, 2021). "According to the latest studies in this field, some ESR1 variants effectively seem to be associated with breast cancer risk, such as rs2234693 and rs9340799, but data from patients of African ancestry or environmental factors were lacking in these analyses." (PMID 33451133, 2021). "Patients with advanced breast cancer were matched to targeted therapies by cfDNA testing for mutations in ESR1, HER2, AKT, and PTEN." (PMID 34392831, 2021). "One of 4 patients with de novo stage IV breast cancer and ESR1 mutation harbored two ESR1 HS mutations (Y537S and E380Q) and the other three had a single mutation." (PMID 33692409, 2021). "This study aimed to investigate the ESR1 PvuII polymorphism as a prognostic and predictive factor guiding the choice of therapy for advanced breast cancer." (PMID 34930150, 2021). "The highest prevalence of ESR1 mutations has been reported in the cell-free DNA (cfDNA) of AI-resistant metastatic ER+ breast cancer patients using droplet digital PCR." (PMID 34638457, 2021). "ctDNA analysis in plasma samples from patients with advanced breast cancer has shown that acquired mutations of ESR1 are a major driver of resistance to fulvestrant/palbociclib combination therapy." (PMID 33535614, 2021). "The high expression of LINC01235 caused the imbalance of ESR1 and led to drug resistance in patients with breast cancer, resulting in a poor prognosis." (PMID 34490040, 2021). "Mutations in PI3K-AKT-mTOR pathway genes are frequently observed in ERα+ breast cancers and at least 50% of breast cancers with ESR1 mutation/amplifications displayed genomic aberrations of this pathway." (PMID 33498407, 2021). "In endocrine therapy resistant breast cancer cells, ESR1 associates with the transcriptional regulator NUPR1 and regulates the transcription of their targets, resulting in enhanced autophagic survival and more malignant behavior." (PMID 33542201, 2021). "A few studies have investigated HLA-J and established that its expression is elevated in breast cancer biopsies and that this is associated with the overexpression of estrogen receptor 1 (ESR1), which has immunosuppressive activities." (PMID 34567510, 2021). "Approximately 25%–40% of metastatic tumors in AI-treated breast cancer (BC) patients have been reported to have ESR1 (ERα) mutations within the ligand binding domain (LBD)." (PMID 34298743, 2021).
breast cancer (continued). "In contrast, ESR1 mutation prevalence is only 4–5% in recurrent breast cancer after prior adjuvant AI (including recurrence while on adjuvant AI), 1.5–7% after neoadjuvant AI, and less than 1% in ET-naïve MBC." (PMID 34392831, 2021). "The ESR1 rs9340799 polymorphism has been frequently investigated with regard to its association with breast cancer (BC) susceptibility, but the findings have been inconclusive." (PMID 34545128, 2021). "FOXA1 missense mutations are enriched in metastatic luminal breast cancers compared to primary lesions and are often mutually exclusive with mutations in ESR1." (PMID 34680352, 2021). "We also found that the minor allele of rs851998, which is located near the ESR1 gene, was associated with an increased risk of breast cancer for females who were taller than 160 cm." (PMID 34069208, 2021). "The next pathway, ESR1, which was mutated in breast cancer, received microenvironment factor S100A4 to regulate TF ETS1 and SMAD3 through signaling transduction proteins ZNF516, PIK3R1, IDH1, and AKT1." (PMID 33802957, 2021). "In conclusion, our results suggest that preexisting ESR1 ET resistance mutations in untreated primary breast cancer are rare but are associated to poor outcome and resistance to standard hormone therapy." (PMID 33937624, 2021). "TRIM3 expression was upregulated in tamoxifen-resistant breast cancer compared with that in tamoxifen-sensitive breast cancer, and was strongly associated with ESR1 SUMOylation." (PMID 34508066, 2021). "In contrast, ESR1 mutations are rare (less < 1%) in primary ERα-positive breast cancers but between 20 and 40% of ESR1 mutations are observed in metastatic breast cancer and influence response to hormone therapy." (PMID 34156490, 2021). "Particularly, the ESR1 mutation dramatically shifts the distribution of metastatic breast cancer destinations with a sharp increase in the liver (from 52% to 75%) accompanied by fractional decreases in brain and lung (p < 0.0001, Chi-squared test)." (PMID 34795255, 2021). "Polymorphisms in the ER gene regions, particularly in the ESR1 region, are implicated in risk for a variety of traits, such as breast cancer, age of menarche, age at first birth, uterine fibroids, endometriosis." (PMID 33806348, 2021). "More than three-quarters of primary breast cancers are positive for estrogen receptor alpha (ER; encoded by the gene ESR1), the most important factor for directing anti-estrogenic endocrine therapy (ET)." (PMID 33937624, 2021). "The PvuII (rs2234693) Single Nucleotide Polymorphism (SNP) in the gene coding for the estrogen receptor-1 (ESR1), has been found associated with outcome in tamoxifen treated patients with early hormone-receptor positive breast cancer." (PMID 33547330, 2021). "A recent report showed the association of ESR1 with ferroptosis in breast cancer, especially in cells with low ESR1 expression." (PMID 35252218, 2021). "An intronic polymorphism in the ESR1 gene (rs2234693), also called ESR1 PvuII, is associated with an increased risk of breast cancer and decreased estrogen receptor (ER) expression." (PMID 34930150, 2021). "With several reports suggesting the association between ESR1 and height, we think that the ESR1 gene and height possibly have an association with breast cancer risk, since significant interaction results were found in our results." (PMID 34069208, 2021). "Here, we demonstrate for the first time that ESR1 mutation is detrimental in primary breast cancer, showing that ESR1 ET resistance mutations that preexist any systemic therapy are associated to poor OS and RFS in patients who receive adjuvant ET." (PMID 33937624, 2021). "A single nucleotide polymorphism (SNP) in intron 1 of this gene called ESR1 PvuII (rs2234693) has been reported to increase the risk of breast cancer." (PMID 34930150, 2021).
breast cancer (continued). "In conclusion, ESR1-e6 gene fusions are part of the spectrum of the somatic mutations that constitutively activate ESR1 proteins in advanced ER+ breast cancer to drive poor outcomes." (PMID 34711608, 2021). "ESR1 is able to mediate the biological effects of the steroid hormone estrogen, while its mutation in breast cancer is a common mechanism of hormonal therapy resistance." (PMID 34055017, 2021). "Breast cancer cells acquire ESR1 mutation following exposure to ET, particularly an AI, and also in combination with CDK4/6i." (PMID 34771560, 2021). "There was a notable difference in the frequency of ESR1 mutations in patients with prior ET (p = 0.05), prior chemotherapy (p = 0.01), or de novo stage IV breast cancer (p = 0.06)." (PMID 33692409, 2021). "Previously, numerous studies have suggested the association between the ESR1 gene and breast cancer, and have reported the role of ESR1 mutations for breast cancer." (PMID 34069208, 2021). "In order to understand processes underlying breast cancer recurrence in tamoxifen-treated patient cohorts, we considered possible interactions and interplay of ESR1 and E2F1." (PMID 33852600, 2021). "Numerous studies in the past years focused on discovering novel therapeutic strategies for the treatment of breast cancers harboring ESR1 mutations." (PMID 33741974, 2021). "The first SERD to be developed and approved for ER+ breast cancer was fulvestrant, demonstrating also interesting activity in ESR1 mutated patients in the second line treatment setting." (PMID 34360578, 2021). "ESR1 gene mutations known to be associated with resistance to aromatase inhibitors in ER-positive metastatic breast cancer were found in two non-responders." (PMID 33837242, 2021). "Breast cancer cells harbouring ESR1 alterations in the region encoding the ligand binding domain have been described in 15–40% of ERα-positive metastatic tumours, while they are rarely present in primary tumours." (PMID 34944934, 2021). "We demonstrated that human ER+ breast cancer cells with a point mutation in the ligand binding domain of ESR1 (encodes ER) had increased expression of CHI3L1 when compared to those with wild type ESR1." (PMID 34832904, 2021). "ESR1 mutations in circulating tumour cells have been used as a predictive factor for breast cancer patients after failure of hormonal therapy." (PMID 34930150, 2021). "Various mechanisms account for the endocrine resistance in ER+ breast cancer, including mutations in ERα gene (ESR1), ERα post-translation modifications, and activation of the phosphatidylinositol 3-kinase (PI3K) pathway or PIK3CA activating mutations." (PMID 34131114, 2021). "In a different example, TWIST has been shown to recruit DNMT3B to the estrogen receptor 1 (ESR1) promoter, resulting in DNAme and loss of ER expression, and the progression of breast cancers that are ER-negative and hormone-resistant." (PMID 34988459, 2021). "The estrogen receptor 1 (ESR1) gene encodes the ERα protein, a ligand regulated transcription factor, which plays a central role in the proliferation of breast cancer." (PMID 34356536, 2021). "Elacestrant has also demonstrated antitumor activity in breast cancer models harboring mutations in estrogen receptor alpha gene (ESR1) known to confer resistance (e.g., Y537S, D538G) and those resistant to cyclin-dependent kinase 4,6 (CDK4/6) inhibitors." (PMID 32912274, 2020). "Oncogenic mutations in ESR1 are common in metastatic and pretreated breast cancer, emerging as a mechanism of acquired resistance to endocrine therapies that can ultimately result in a lack of response to the combinational therapy." (PMID 32907621, 2020). "Numerous preclinical and clinical data suggest that combination of cyclin inhibitors with SERD would improve the anti-tumoral efficacy especially in advanced breast cancer expressing ESR1 mutations." (PMID 32601772, 2020).